CRP (C-reactive protein)
Diseases named in the same sentence as CRP in open-access papers (continued):
Sharing a sentence is not in itself a finding about the gene and the disease.
Q fever (8 papers, 2015 to 2025). A bacterial infection caused by Coxiella burnetii. "Male sex, middle age (30–60 years), headache, leukocyte count < 10 G/L, and C-reactive protein (CRP) level > 185 mg/L were thus independently associated with Q fever and were used in the predictive score." (PMID 35977720, 2022). "In multivariate analysis, living in Cayenne area, being aged 30–60 years, C-reactive protein (CRP) > 185 mg/L, and leukocyte count < 10 G/L were independently associated with Q fever." (PMID 35977720, 2022). "In the multivariate analysis, living in Cayenne area, being aged between 30 and 60 years old, having a CRP levels > 187 mg/L, and having WBC counts <10 G/L were independently associated with Q fever." (PMID 35977720, 2022). "In subgroup analysis of acute Q fever patients, those with delayed defervescence had higher CRP and PCT values in both acute and convalescent phase, though not reaching statistical significance." (PMID 32398008, 2020). "In the subgroup analysis of 115 patients with acute Q fever, CRP and PCT values within 7 days of onset of acute Q fever were positively correlated, and both markers were positively correlated with the AST value significantly, which was not previously reported." (PMID 32398008, 2020). "C-reactive protein (CRP) tended to be higher in patients with acute Q fever compared to the control group (mean 154 mg/l vs. 113 mg/l, P = 0.068), but other laboratory findings were similar." (PMID 30869006, 2019). "The acute phase protein C-reactive protein is elevated in various inflammatory conditions including Q fever and is determined during treatment to monitor disease activity." (PMID 28793883, 2017). "Patients with acute Q fever had a higher levels of C-reactive protein (mean 167 mg/L vs. 117 mg/L; p = 0.02) and lower leukocyte counts (mean 9.0 × 109 cells/L vs. 11.5 × 109 cells/L; p = 0.006)." (PMID 26196955, 2015). "Patients with acute Q fever were younger and had higher C-reactive protein levels but lower leukocyte counts." (PMID 26196955, 2015). "The increased transaminase values might reflect disease severity of acute Q fever based on the correlation between CRP, PCT and AST values." (PMID 32398008, 2020). "Reportedly, CRP is high in the acute stage of acute Q fever." (PMID 28793883, 2017). "Traditional markers for diagnosing and monitoring chronic Q fever are anti-phase I IgG titers, reflecting a specific B-cell derived humoral immune response and CRP, a product of an aspecific IL-6 mediated inflammatory response, used to detect complications and concomitant infections." (PMID 28793883, 2017). "Correlation analysis of CRP, PCT, AST and WBC values with days from doxycycline treatment to defervescence was also conducted in the subgroup analysis of acute Q fever patients; the laboratory data were obtained within 7 days after the disease onset." (PMID 32398008, 2020). "The prognostic score derived from multivariable logistic regression included male sex, age 30–60 years, a low leukocyte count and a high C-reactive protein (CRP) level, along with headache, as predictors of Q fever pneumonia." (PMID 32957938, 2020). "All these results suggested that CRP, PCT and WBC values could be predictors for treatment response of acute Q fever." (PMID 32398008, 2020). "In acute Q-fever IL-6 and CRP seemed predictive of more severe disease, but no support was found that these were associated with prolonged fatigue." (PMID 27223465, 2016). "In addition to the positive correlation between the values of CRP, PCT and WBC, their values within 7 days from disease onset were also significantly and positively correlated with the days from doxycycline treatment to defervescence in acute Q fever." (PMID 32398008, 2020). "However, as we have shown, CRP is undetectable in most samples of chronic Q fever patients and therefore not a suitable marker for disease remission in chronic Q fever." (PMID 28793883, 2017).
Skin rash (8 papers, 2015 to 2025). A red eruption of the skin. "Polymorphous skin rash and high CRP were found to be independently associated with complete KD." (PMID 41042754, 2025). "The most common symptoms of the MCTD activity were as follows: swelling fingers or hands (92% of MCTD patients), decreased number of leukocytes and/or platelets, increased ESR and/or CRP levels, hypergammaglobulinemia, and skin rashes." (PMID 33430976, 2021). "In murine typhus, PMN counts correlated well (Spearman’s Rho, p-value) with plasma levels of protein C (Rho = 0.37, p = 0.0089), CRP (Rho = 0.31, p = 0.0026), and the presence of skin rash (Rho = 0.23, p = 0.031), but not with ELA complex levels (p = 0.074)." (PMID 26317419, 2015).
stomach cancer (8 papers, 1983 to 2025). "Weiet al. observed significant declines in leukocyte and CRP levels on patients who received ω-3-enriched IVLE for 6 days after undergoing gastric tumor resection." (PMID 33299555, 2020). "However, as the fever and CRP level dramatically improved after the surgery, the gastric tumors were clearly related to the main complaints." (PMID 28276003, 2017).
adult-onset Still disease (7 papers, 2020 to 2025). A rare inflammatory multisystem disorder characterized clinically by fever of unknown origin, arthralgia or arthritis, hyperleucocytosis, and typical skin rash. "The multimodal approach was also effective in handling outliers, such as a control patient with adult-onset Still disease in remission, who exhibited markedly high saliva CRP values despite low serum and urine CRP levels." (PMID 40856619, 2025). "AOSD, adult-onset Still’s disease; CRP, C-reactive protein; ESR, erythrocyte sedimentation rate; SD, standard deviation." (PMID 36899416, 2023).
agranulocytosis (7 papers, 2016 to 2023). "From the admission day he remained in agranulocytosis and developed febrile infection with CRP 17.9 mg/L and PCT 22.3 ng/mL." (PMID 28324282, 2017). "On the 3rd day of agranulocytosis, a high fever appeared with increased CRP (74 mg/L) and PCT (17.3 ng/mL)." (PMID 28324282, 2017). "Among the 88 patients in the single-positive group who were treated with antibiotics, we assessed the WBC count, percentage of neutrophils (N%), C-reactive protein (CRP) level, and procalcitonin (PCT) level according to the presence of infection and agranulocytosis." (PMID 36877734, 2023). "Last, CRP and PIP were independently related to agranulocytosis." (PMID 34307258, 2021). "The total length of hospital stay, peak inspiratory pressure (PIP), VIS, CRP, and PCT in the agranulocytosis group were significantly higher than those in the non-agranulocytosis group (P < 0.05)." (PMID 34307258, 2021).
antiphospholipid syndrome (7 papers, 2010 to 2025). A disorder caused by the presence of autoantibodies directed against phospholipids, causing a hypercoaguable state, which may result in blood clots, stroke, heart attack, and in women, significant pregnancy-related complications, including miscarriage and still birth. "Erroneous test results in lupus anticoagulant in antiphospholipid syndrome because of CRP have been reported in the current literature [1192]." (PMID 37873776, 2023). "On the other hand, since SLE and antiphospholipid syndrome cases also present anti-CRP antibodies, one could argue that these may actually be immunocomplexes that were not washed enough." (PMID 37873776, 2023). "Additional assessments, including urinalysis, stool analysis, C-reactive protein (CRP), erythrocyte sedimentation rate (ESR), lupus anticoagulant, antiphospholipid syndrome markers, direct antiglobulin test, and complement C3/C4 levels, were within normal limits." (PMID 40491913, 2025).
Apathy (7 papers, 2013 to 2022). Apathy is a quantitative reduction of interest, motivation and the initiation and persistence of goal-directed behavior, where often the accompanying emotions, thoughts, and social interactions are also diminished. "In our CCMA cohort, we found that IL-6 level, but not CRP, was significantly associated with apathy, which differs from Eurelings’ previous findings that CRP was associated with apathy in the PreDIVA trial." (PMID 35742625, 2022). "A population-based cohort study found increased CRP levels remained associated with apathy symptoms after adjustment for demographics and depressive symptoms." (PMID 35183116, 2022). "Eurelings and her colleagues suggested that C-reactive protein levels (CRP) are associated with apathy in the preDIVA trial with older adults with cardiovascular risk." (PMID 35742625, 2022). "Moreover, when we excluded the 48 participants with a eGFR < 30 ml/min/1.73 m2 from the analyses, the eGFR was still inversely associated with apathy (β = -0.054, p = 0.01), independently from CRP and all other covariates." (PMID 28081723, 2017). "Recently, deep white matter lesions mediated the relationship between CRP and apathy in community dwelling older adults." (PMID 35742625, 2022). "Yao’s study revealed that the mediating effects of deep white matter lesions in the relationship between CRP and apathy in community dwelling older adults." (PMID 35742625, 2022). "The inflammatory biomarker IL-6 was significantly associated with the higher levels of apathy while CRP was not." (PMID 35742625, 2022). "Linear and logic regression models showed that IL-6, but not CRP was significantly associated with apathy adjusted for age, gender, and years of education (β = 0.037, 95% CI: 0.002–0.072, p = 0.04)." (PMID 35742625, 2022). "Apathy showed the strongest independent relation with both low eGFR and high hs-CRP." (PMID 28081723, 2017). "In regression models, IL-6 but not CRP was associated with apathy." (PMID 35742625, 2022). "However, this hypothesis was only partly supported by our results which show that the relation between eGFR and apathy symptoms is largely independent of CRP levels." (PMID 28081723, 2017).
aspergillosis (7 papers, 2020 to 2024). Aspergillosis is an infection, growth, or allergic response caused by the Aspergillus fungus. "One example is CRP that was also found to be prominently increased during aspergillosis in previous studies." (PMID 33043780, 2020). "There are limited data on PCT, sTREM-1, C-reactive protein (CRP), lactate dehydrogenase (LDH), erythrocyte sedimentation rate (ESR) levels, and white blood cells (WBC) count in the diagnosis of aspergillosis." (PMID 36320074, 2022). "However, cases of influenza-associated aspergillosis are usually more likely to have H1N1 subtypes and higher levels of C-reactive protein and interleukin-6 than cases without aspergillosis." (PMID 35628717, 2022).
Atrophy (7 papers, 2006 to 2025). Any weakening or degeneration, especially through lack of use. "Other markers include neopterin and C-reactive protein (CRP), early inflammation molecules that increase significantly in IM and atrophy compared with chronic gastritis alone." (PMID 37063848, 2023). "We observed that patients with orchiectomy or atrophy had significantly higher values of leukocytes and neutrophils, as well as inflammatory indices (NLR, PLR, SIRI and IBS) and CRP." (PMID 40710427, 2025). "DNAm CRP exhibited significantly larger (6.4-fold, on average) associations with brain structural MRI metrics (including global GM and WM atrophy, poorer WM microstructure, and increased WMH burden) than serum CRP." (PMID 34789543, 2021).
bone neoplasm (7 papers, 2013 to 2024). A benign, intermediate, or malignant neoplasm involving the bone or articular cartilage. "In a meta-analysis of five studies with a total of 816 patients with bone neoplasm, higher levels of preoperative CRP levels were associated with reduced OS." (PMID 39001318, 2024). "By combining the HRs and 95% CIs from all studies, we showed the association between preoperational serum levels of CRP and the overall survival of patients with bone neoplasms." (PMID 29668751, 2018). "The aim of this study was to conduct a meta-analysis of retrospective studies that investigated the association of preoperative C-reactive protein (CRP) levels with the overall survival (OS) of patients with bone neoplasms." (PMID 29668751, 2018). "This may be due to the differences in the susceptibility genes, treatment options, and CRP measurement methods of bone tumors in Asia and Europe." (PMID 34720749, 2021). "The random effects model showed a significant relationship between elevated levels of CRP and OS in patients with bone neoplasms (HR: 1.87; 95% CI: 1.28–2.75; P = 0.001), with heterogeneity (I2 = 62.4%, P = 0.031)." (PMID 29668751, 2018). "The results of this meta-analysis suggest that increased CRP expression indicates a poorer prognosis in patients with bone neoplasms." (PMID 29668751, 2018). "While multiple studies have been carried out, the relationship between CRP and the prognosis of bone cancer remains controversial, with end results varying among studies." (PMID 29668751, 2018). "In a pooled analysis of all the publications, increased serum CRP levels had an adverse prognostic effect on the overall survival of patients with bone neoplasms." (PMID 29668751, 2018). "The results of this meta-analysis support increased levels of CRP as a prognostic factor for OS in bone cancer, which agrees with the results of most studies." (PMID 29668751, 2018). "A summary of HRs for the overall and subgroup analyses of CRP levels in patients with bone neoplasms." (PMID 29668751, 2018). "More prospective studies are needed to confirm the prognostic significance of CRP levels in patients with bone neoplasms." (PMID 29668751, 2018). "The five selected studies provided the levels of CRP before treatment and OS in patients with bone neoplasms." (PMID 29668751, 2018). "We extracted the data from these studies and combined the hazard ratios (HR) and 95% confidence intervals (CIs) to assess the correlation between CRP levels and OS in patients with bone neoplasms." (PMID 29668751, 2018). "To evaluate the significance of the preoperative level of CRP for the outcome of bone cancer patients, we did a systematic review and meta-analysis using updated data on individual patients from all available trials." (PMID 29668751, 2018). "First, the susceptibility genes for bone neoplasms in Asia are different from those in Europe, which might lead to different levels of CRP in patients with bone neoplasms." (PMID 29668751, 2018). "Our result revealed that higher levels of CRP are associated with shorter OS, with an HR of 1.87 (95% CI: 1.28–2.75; P = 0.001), indicating that high serum levels of CRP before treatment may be a negative prognostic factor for patients with bone cancers." (PMID 29668751, 2018). "Generally, our meta-analysis demonstrated the prognostic value of increased preoperative levels of CRP for poorer OS in patients with bone cancer in Europe but not in Asia." (PMID 29668751, 2018).
bone sarcoma (7 papers, 2016 to 2023). A sarcoma that arises from the bone. "Systemic inflammation is strongly associated with cancer development and progression, and serum CRP levels are directly associated with a worse outcome in many different malignancies, including bone sarcomas." (PMID 36143059, 2022). "In bone sarcomas, both the survival and recurrence have shown significant associations with pre-operative CRP values." (PMID 27091202, 2016). "However, CRP was not a routine examination as part of the pretreatment assessment of patients with bone sarcoma in many hospitals." (PMID 33897913, 2021).
cholangiocarcinoma (7 papers, 2016 to 2024). A carcinoma that arises from the intrahepatic biliary tree (intrahepatic cholangiocarcinoma) or from the junction, or adjacent to the junction, of the right and left hepatic ducts (hilar cholangiocarcinoma). "For example, IL-6, one of the main inducers of CRP production, has been shown to be associated with development and progression of cholangiocarcinoma and other cancers." (PMID 27733196, 2016).
chronic gastritis (7 papers, 2019 to 2025). Inflammation of the stomach that is chronic in nature. "Serum CRP has been reported as increased in dogs diagnosed with GC as compared to dogs with chronic gastritis and control dogs." (PMID 33563310, 2021). "H. pylori infection causes chronic gastritis and induces an inflammatory response that increases the pro-inflammatory factors interleukins (IL-1β, IL-6, IL-8, IL-17), tumour necrosis factor α (TNF-α), interferon γ (IFN-γ), and C-reactive protein (CRP)." (PMID 38475712, 2024). "Moreover, dogs with GC can present with increased levels of serum C-reactive protein (CRP) and decreased serum folate concentrations as compared to dogs with chronic gastritis and healthy controls." (PMID 33563310, 2021).
chronic hepatitis B (7 papers, 2013 to 2024). "Regarding severe disease course, CLD and chronic hepatitis B infection were proven to be highly specific, and platelet count and ALT and AST activities were moderately specific, whereas CRP was highly sensitive." (PMID 33282888, 2020). "The result of this study demonstrates that supplementation of vitamin A at low and high dosages for short and long durations increases the CRP plasma concentrations on adults and vitamin A supplementation decreases the TNF-α concentrations in chronic hepatitis B on adults." (PMID 36496428, 2022).
coronary vasospasm (7 papers, 2013 to 2025). Sudden coronary artery smooth muscle contraction leading to lumen constriction and decreased blood flow. "But the association between coronary vasospasm and inflammatory makers such as hs-CRP and peripheral monocyte count was more complicated." (PMID 24737995, 2014). "As renal function downhill from CKD stage 1 to stage 3, more uremic toxins accumulate and then possible the association between hs-CRP and coronary vasospasm lost its significance." (PMID 24737995, 2014). "A total of 8 variables were significantly associated with coronary vasospasm, namely, age, male gender, cigarette smoking, peripheral white blood cell count, peripheral blood monocyte count, haemoglobin, creatinine, and hs-CRP." (PMID 24737995, 2014). "The correlation of risk of coronary vasospasm and hs-CRP was different in CKD stage 1, stage 2, and stage 3." (PMID 24737995, 2014). "But the association between coronary vasospasm and hs-CRP lost significance in CKD stage 2 and stage 3 patients." (PMID 24737995, 2014). "The results of multivariate logistic regression analysis revealed that peripheral blood monocyte count and hs-CRP level were independently associated with coronary vasospasm in patients with stage 1 CKD." (PMID 24737995, 2014). "In addition, high-sensitivity CRP increased IL-6 level, p38MAPK expression, and monocyte activation, which contribute to coronary artery spasm, whereas the overexpression of the monocytic α7 n Ach receptor decreases oxidative stress and inflammation-associated coronary artery spasm." (PMID 35425785, 2022). "Peripheral blood monocyte count is independently associated with the development of coronary vasospasm in patients with CKD stages 1–3 and hs-CRP is independently associated with coronary vasospasm in patients with CKD stage 1." (PMID 24737995, 2014). "In CKD stage 3 patients, the serum hs-CRP levels were around 7.5–15.0 mg/L and the association of hs-CRP and coronary vasospasm was not significantly obvious." (PMID 24737995, 2014). "Only peripheral blood monocyte count but not hs-CRP was independently associated with coronary vasospasm in patients with stages 2 and 3 of CKD." (PMID 24737995, 2014).